IL6 (interleukin 6)
Diseases named in the same sentence as IL6 in open-access papers (continued):
Sharing a sentence is not in itself a finding about the gene and the disease.
cancer (continued). "Pro-inflammatory cytokines, in particular TNF-α and IL-6, trigger the production of cyclooxygenase 2 (COX2 or PTGS2), which in turn produces prostaglandin E2 (PGE2), favoring cancer progression." (PMID 31766196, 2019). "Cytokines such as TNF-α, IL-1, IL-6, and interferon-gamma (IFN-γ) are released by both cancer cells and host immune cells (macrophages/lymphocytes)." (PMID 31683709, 2019). "Serum of mice that had received cancer cells secreting IL-15sol showed significantly elevated levels for Eotaxin, G-CSF, IFN-γ, IL-1α, IL-5, IL-6, IP-10, KC, MCP-1 and MIG." (PMID 31856922, 2019). "In BCC, the interaction of HH/GLI and pro-inflammatory IL6/signal transducer and activator of transcription-3 (STAT3) signaling synergistically regulates common GLI-STAT3 target genes and promotes cancer proliferation." (PMID 31878932, 2019). "Collectively, oncogenic MCT-1 activation stimulates the IL-6/IL-6R/Stat3 axis that enhances EMT progression, cancer stemness and M2 polarization in the TNBC system." (PMID 30885232, 2019). "For example, BIRC5 (also known as Survivin) and BCL2 are anti-apoptotic genes that promote cancer cell survival, whereas IL17A, IL23 and IL6 play important roles in promoting pro-inflammatory oncogenic signaling." (PMID 31292446, 2019). "IL-1β, IL-6, TNF-α, IL-4, IL-10, and TGF-β are among the most well studied cytokines known to effect cancer initiation/progression and sleep." (PMID 31174326, 2019). "In particular, Adenosine 5-triphosphate sodium hydrate (ATP), Sodium Lactate, and Human Interleukin 6 (IL6) were detected, whose concentration can be connected to cell metabolism disorders of cancer cells and can be used as biomarkers in cancer therapies." (PMID 30832416, 2019). "To confirm that STAT3 signalling was activated in epidural ADSCs in response to paracrine secretion from cancer cells, we evaluated STAT3 phosphorylation in ADSCs after the addition of recombinant IL-6, IL-11 and LIF by western blot." (PMID 31196220, 2019). "There are a variety of studies that have tested different inflammatory markers in cancer or neutropenic patients such as PCT, CRP, and IL-6." (PMID 30796468, 2019). "Immune system associated pathways, such as interferon alpha and gamma signaling, IL6 JAK STAT3 signaling, TNFA signaling through NFKB and MTORC1 signaling, were found to be upregulated in both ASD and 55%, 55%, 41%, 41% and 63% of cancer types, respectively." (PMID 31007884, 2019). "The results here reported demonstrate novel biological properties of LPE that are able to prevent IL-6-induced invasiveness, to reduced IL-6-stimulated MMP-9/2 up-regulation in gastric MKN-28 and AGS cancer cell lines, and to inhibit in vitro AChE activity." (PMID 31817563, 2019). "Human endothelial cells stimulated with microparticles obtained from cancer patients post-VEGFi treatment induced a significant increase in gene expression of pro-inflammatory markers including TNF-α, IL-6, MCP-1, iNOS, COX-2, and VCAM-1." (PMID 30753341, 2019). "Previous studies have reported that IL-6 or IL-6 downstream signaling confers chemotherapeutic resistance by triggering the PI3K/Akt, MAPK/ERK, or Jak1/STAT3 signaling pathway in cancer cells." (PMID 30927911, 2019). "An interplay between the IL-6/11-STAT3 pathway and EMT has been extensively studied in different cancer types." (PMID 31123345, 2019). "Novel agents that target IL-6 and its signaling pathway, including ROCKs and STAT3, have undergone clinical or preclinical trials in cancer." (PMID 31462327, 2019).
cancer (continued). "As previously extensively discussed, IL-6 has been noted as being particularly relevant to fatigue, in relation to IFN-α induced symptoms as well as other clinical contexts including cancer." (PMID 30567628, 2019). "However, for IL-8, IL-6, and IP-10, which show a synergistic increase, the experimental design does not allow us to identify whether stromal cells stimulate their release from cancer cells or cancer cells stimulate their release from stromal cells." (PMID 31769424, 2019). "Our present findings show that vincristine treatment of cocultured cancer and CAF-like cells resulted in increased secretion of IL-6 and TGF-βs, both known as EMT inducers." (PMID 31010006, 2019). "Various factors, including PIF (tumor-derived factor), myostatin (skeletal muscle-derived factor), and cytokines, such as TNF-α and IL-6, can facilitate skeletal muscle depletion by inhibiting the PI3K/Akt signaling in cancer cachexia." (PMID 30754663, 2019). "It has been also observed that CAFs constitute a major stromal compartment actively communicate with cancer cells through growth factors or inflammatory cytokines such as HGF, IL-6, TGF-β, VEGF, FGF, and CXCL12 that can promote tumorigenesis and progression." (PMID 31024835, 2019). "IL-6, JAK1, JAK2 and STAT3 which are considered main components of this pathway, have been found to be overexpressed in different cancers, including BCC." (PMID 31342143, 2019). "Some studies have found that the expression of IL-6 cytokine family proteins, including OSM, in cancer-related fibroblasts is approximately 100 times higher than that in normal fibroblasts." (PMID 31871447, 2019). "Conversely, robust STAT3 signaling activity in M2-TAMs and N2-TANs correlates with the production of factors able to drive cancer cell EMT (OSM, IL-6, TGF-β) and angiogenesis (VEGF, TGF-β, PDGF, and FGF)." (PMID 31684144, 2019). "Other research groups also found that in cancer cells the EGFR inhibitors erlotinib and dacomitinib can activate the interleukin-6 (IL6) / JAK / STAT3 signaling pathway, thereby leading to drug resistance." (PMID 30674340, 2019). "More specifically, SPHK1/2 KD is involved in the inhibition of IL-6 production in MCF7 cells, thus reducing cancer-mediated inflammation." (PMID 31817453, 2019). "In general, immune-related cells produce various cytokines, e.g., IL-6, TNFα and IFNγ, and free radicals (H2O2 and NO) that exert tumoricidal activity on tumors or cancer cells." (PMID 31041568, 2019). "Studies have shown that inflammatory factors (especially IL-6 and TNF-α) play an important role in the occurrence and development of cancer cachexia." (PMID 31788012, 2019). "The complex IL-6/IL-6 receptor induces the PI3K/AKT pathway, which results in the enhancement of cancer cell proliferation and an anti-apoptotic effect." (PMID 31766196, 2019). "Secondly, together with TNFα, IL6 is a major inflammation inducer which activates STAT3, resulting in cancer progression." (PMID 31398937, 2019). "IL-6 enhanced the effect of MCT-1 on EMT plasticity, M2 polarity and cancer stemness, which were suppressed by tocilizumab." (PMID 30885232, 2019). "Similar to our CVL findings, other researchers found significantly increased levels of IL-6, VEGF, HGF and OPN in both cancer patients’ sera and cancerous tissues." (PMID 31089160, 2019). "Several studies have shown that higher DII score is associated with elevated levels of inflammatory mediators, which include TNF-α, IL-6 and hs-CRP, indicating strong link between DII and cancer." (PMID 31652856, 2019). "It has been proposed that this type of MDP delivery activates tumoricidal activity of macrophages by triggering the secretion of cytokines (IL‐1, IL‐6, and TNF‐α) and other soluble mediators leading to final eradication of cancer cells." (PMID 30548868, 2019). "The upregulated IL-6 mediates resistance to anti-VEGF therapy, leading to the proliferation of cancer cells and dysfunctional angiogenesis." (PMID 31474975, 2019).
cancer (continued). "The analysis demonstrated that expression of four of six proteins (CCL13, IL‐6, CXCL17, and DCN) also differed between the benign lesions and cancer." (PMID 30451357, 2019). "Many of the key drivers of neoplastic progression, such as neutrophils, MDSCs, TAMs, and Tregs cells, work by secretion of pro-inflammatory cytokines, including IL-1, IL-6, TNF, and TGF-β, providing a basis for a link between inflammation and cancer." (PMID 31769418, 2019). "Curcumin was shown to downregulate NF-κB and inhibit the interleukin-6 (IL-6)-mediated phosphorylation of STAT3, thus inhibiting the proliferation of the cancer cells." (PMID 30818786, 2019). "For instance, piceatannol suppresses the proliferation of cancer cells by mitochondria-mediated intrinsic pathways, including the PI3K/AKT1/mTOR, spleen tyrosine kinase, cyclooxygenase-2, and IL-6/STAT3 pathways." (PMID 31517069, 2019). "SOD2 was also essential for the invasion of un-irradiated cancer cells induced by upregulation of Bcl-XL, an intracellular oncogene, or extracellular factors, such as SULF2 and IL-6." (PMID 30755594, 2019). "Collectively, these data suggest that a positive feedback loop between IL6 from TAMs and CCL2 from TAMs-educated CRC cells promotes the EMT of cancer cells and the recruitment of macrophages." (PMID 30927925, 2019). "To ascertain the contribution of IL‐6 signaling on cancer cells to this effect, we knocked down IL‐6 receptor (IL6RA) in the TGFβR2‐mutant cells and evaluated the efficacy of TGFβR2 and IL‐6 inhibition in vitro and in vivo." (PMID 31609088, 2019). "This suggests that TGFβ signaling promotes the secretion of IL‐6 from stromal cells, which then induces STAT3 activation in PDA cancer cells." (PMID 31609088, 2019). "During cancer, the ROS and other stress conditions such as COX-2, PGE2, pro-inflammatory cytokines like TNF-α, IL-1β, IL-6, and another NF-kB modulator take part in facilitating the activation of nuclear translocation of NF-kB via numerous mechanisms." (PMID 31556759, 2019). "mPD-L1/mPD-1 can be induced by multiple inflammatory cytokines in cancer, including IFN-γ, IL-6, IL-10, IL-17 and TNF-α." (PMID 30506460, 2019). "Like IL-6, IL-11 can drive a STAT3-mediated regenerative program in epithelial cells, a function that promotes malignancy in cancers of the intestine, stomach, and mammary gland." (PMID 31156640, 2019). "GLI1 binds to IL-6 promoter and fibroblasts-secreted IL-6 regulates activation of STAT3 in cancer cells." (PMID 31847096, 2019). "Among all the cytokines that were measured, the concentration of IL-6, MCP-1 and IL-12p70 in the group of cancer control (CC) were found to have a significant increase throughout the four weeks compared with normal control." (PMID 30947706, 2019). "Previous studies suggested that the activated stroma secretes large amounts of IL-6, VEGF, and SDF-1, resulting in a significant enhancement in invasion of the surrounding cancer cells." (PMID 30800209, 2019). "Autocrine IL-6/STAT3 signaling fuels CAFs proliferation and stimulates the horizontal transfer of miR-221/222high microvescicles to cancer cells." (PMID 30927908, 2019). "Nonetheless, our analysis revealed a correlation between high IL6/ATCA2 mRNA levels and poor cancer specific survival." (PMID 30744595, 2019). "Given that ROS overproduction and antioxidant enzyme activities reduction play an important role in the inflammatory response in cancer cells, we measured the levels of cytokines as TNF-α and IL-6 within HCT 116 cells using ELISA test." (PMID 31269760, 2019). "Immunogenicity in vitro was analyzed by co-culturing of dying cancer cells with bone-marrow derived dendritic cells (BMDCs) and rate of phagocytosis and maturation (CD11c+CD86+, CD11c+CD40+) of BMDCs and production of IL-6 in the supernatant were measured." (PMID 31842994, 2019). "This phenomenon, where both IL-6 secretion and EGFR levels are often elevated, creates a perfect environment for cancer development and progression." (PMID 31470515, 2019).
cancer (continued). "We and other have shown that IL-6 and CXCL8/IL-8 play a critical role in the epithelial to mesenchymal transition of human carcinoma cells." (PMID 31741710, 2019). "Some pro-inflammatory cytokines, like IL-6, have been shown to stimulate phenotypes consistent with EMT in transformed epithelial cells as well as in carcinoma cell lines." (PMID 31337349, 2019). "The IL-6/IL-6R/JAK/STAT3 is one of these pathways, which contributes to the development and progression of HNC cancers." (PMID 29951282, 2018). "Both PNS and its complexes significantly exerted a lowering effect on the IL-6 secretion in LPS-stimulated macrophages and showed a moderate cytotoxic effect against MCF-7 and HeLa cancer cell lines in vitro." (PMID 29385698, 2018). "In our study, the cancer cells provoked M2 phenotype as demonstrated by an increase of CD163 and Arg1 and a decrease of IL-1b and IL-6 expression." (PMID 30180849, 2018). "We showed that fibrinogen, interleukin-6, factor VIII, D-dimers, VWF, free TFPI and extracellular DNA were higher in cancer patients than in both CP and IPMN patients." (PMID 29899870, 2018). "To date, many studies have showed that the IL-6/Janus kinase/STAT3 signaling pathways are involved in drug resistance, angiogenesis, migration, and other processes in cancers." (PMID 30202238, 2018). "Furthermore, considering that cell differentiation and apoptosis process could be controlled by proinflammatory cytokines, the next step was to evaluate the main proinflammatory cytokines described as responsible for the depletion of AT during cancer cachexia, in particular, IL-6 and TNF-α." (PMID 30094378, 2018). "When starved cancer cells undergo ER stress, NF-κB and STAT3 work together to drive IL-6 expression." (PMID 30186868, 2018). "Here our study reveals that EC-derived IL-6 promotes macrophage alternative activation and GBM progression in vivo, therefore identifying a vascular niche that controls macrophage functions in cancer." (PMID 29422647, 2018). "The IL6, phosphorylated JAK2, phosphorylated STAT3 and SOX2 protein levels in 97L cancer cells were greatly elevated by SHH treatment." (PMID 29722127, 2018). "PN has been reported to exhibit inhibitory activity on the IL-6-induced STAT3 activation, which contributes to its anti-inflammation and anti-cancer properties." (PMID 29921758, 2018). "However, residual confounding could have occurred in these studies, since part of the age association with IL-6 in HNC patients could be due to the presence of occult second primary cancer at the time of HNC diagnosis, a condition associated with increased IL-6 serum levels." (PMID 29951282, 2018). "CM contains high levels of IL-6, which promotes DNA-repair and prevents apoptosis after irradiation in non-small lung cancer (NSCLC)-cells by affecting the self-renewal capacity of cancer stem cells." (PMID 29423072, 2018). "25(OH)D pretreatment inhibits both UV- and tumor necrosis factor alpha (TNF-α)-stimulated IL-6 production in normal cells via p38 MAPK inhibition, demonstrating its significant anti-inflammatory effects in cancer cells." (PMID 30216977, 2018). "Conversely, decreased MUC2 expression contributes to CRC by promoting interleukin-6-induced epithelial to mesenchymal transition (EMT), thereby influencing the invasiveness of cancer cells." (PMID 29967641, 2018). "CAFs produce growth factors (e.g., vascular endothelial growth factor (VEGF)) and cytokines (e.g., TGFβ, IL-6, IL-10) that activate the adjacent ECM, contributing to cancer cell growth." (PMID 30309355, 2018). "Correspondingly, HeLa cells were treated with FSK and probed for its effect on potent established cancer markers like PP2B, IL-6, NOS2, Caspase3, Bcl2, and Bax." (PMID 30558287, 2018). "The proinflammatory pathways that are involved in these processes and provide a mechanistic link between inflammation and cancer include but not limited to, NF-κB, TNF-α, IL-6/STAT3, cyclooxygenase-2 (COX-2)/PGE2, and IL-23/Th17." (PMID 30728783, 2018).
cancer (continued). "Despite that both IL-6 and CXCL1 induced the senescent phenotype of CAFs, CXCL1 secretion showed a cancer-specific response to transform NOFs into CAFs in OSCC, whereas IL-6 secretion was eventuated by common co-culture condition." (PMID 29360827, 2018). "pUS28 activates a variety of signaling cascades that can function to promote cancer, including PLC, cyclooxygenase 2 (COX2) via NFκB, Wnt, hypoxia-inducible factor 1α (HIF1α), and the STAT3-interleukin 6 (IL6) axis." (PMID 30127279, 2018). "Chronic inflammation as mediated by interleukin-6 (IL-6) and tumor necrosis factor alpha (TNF-α) has been widely investigated as an important regulator of fat wasting in cancer cachexia." (PMID 29338749, 2018). "IL-6 can further coordinate with milk-fat globule-epidermal growth factor-VIII produced by macrophages to trigger STAT3 and Sonic Hedgehog pathways in cancer stem cells, thus amplifying their drug resistance." (PMID 30619850, 2018). "A high level of IL-6 and COX-2 is closely related to the growth, migration, and invasion of cancer cells." (PMID 30647533, 2018). "IL-6 also activates STAT-3 to promote VEGF protein expression, angiogenesis, and the growth of cancer cells." (PMID 29794990, 2018). "TLR4-transient knockdown cells had a reduction of intrinsic expressions of IL-6, IL-8 and XIAP in both cancer cells." (PMID 29486738, 2018). "CAFs actively communicated with cancer cells and promoted tumor progression through cytokines such as HGF, IL-6, TGF-β, VEGF, FGF, and CXCL128–10." (PMID 30158543, 2018). "IL-6/JAK/STAT3 pathway was shown to activate EMT through upregulation of Twist, N-cadherin and Vimentin in some types of cancer." (PMID 29581838, 2018). "IL-33-stimulated cancer cells produce cytokines, and TME infiltrating immune cells are also involved in the expression of IL-6 in response to IL-33/ST2 signaling." (PMID 30416507, 2018). "Several inflammatory mediators, such as, IL-6, IL-10, and TGF-β, have been shown to be involved in both the initiation and progression of cancer." (PMID 29783672, 2018). "(a) Chemotherapy can induce endothelial cells to secrete IL6 and tissue inhibitor of metallopeptidase (TIMP1), creating an environment that increases cancer cell survival." (PMID 30373101, 2018). "IL-6 has pleiotropic effects in the TME and also mediates chemoresistance by promoting EMT of cancer cells." (PMID 30356656, 2018). "Consolidating the fusion-based and the RTK-based mechanisms of IL6/JAK/STAT3 activation, we reconstructed a candidate pathway driving patient 1’s cancer (Appendix Fig A4)." (PMID 31372595, 2018). "In a recent study, MHC class II expression of Th1 cells was blocked by IL-6, hampering the secretion of IFN-γ and IL-2, thereby reducing the cytotoxic T-lymphocyte activity, enabling the cancer cells to evade the anticancer immunological reaction." (PMID 30038723, 2018). "We documented that IL-6 secreted by IR cells activates the JAK2 and STAT3 pathway through IL-6 receptor in cancer cells, leading to the IGF-1Ec upregulation and PEc secretion, as well as to the IL-6 expression and secretion." (PMID 30134795, 2018). "IL-6 activates many signaling molecules, including those in the pathways of PI3K, JAK-STAT, and MAPK, which affect the development of cancer." (PMID 29794990, 2018). "For example, inflammatory cytokines, such as IL-6 and TNF-α, are induced in a cancerous environment and induce cancer progression." (PMID 29415668, 2018). "Such TAMs are then able to produce IL-10, VEGF, IL-6, and MMP9 which promote proliferation and invasiveness of cancer cells." (PMID 30416507, 2018). "Several clinical studies indicate that overexpression of inflammatory cytokines, such as IL-1, IL8, IL6 or CXCL1, correlates with cancer progression and decreased response to EGFR targeting therapy." (PMID 30261609, 2018).